JAG2 (jagged canonical Notch ligand 2)
Diseases named in the same sentence as JAG2 in open-access papers (continued):
Sharing a sentence is not in itself a finding about the gene and the disease.
cancer (continued). "As there are many Notch ligands—Jag1, Jag2, DLL1, DLL3, and DLL454—we wanted to identify which Notch ligand(s) is/are involved in stemness induction in cancer cells." (PMID 34911937, 2021). "Given that c-MYC is a well-known driver of oncogenesis in many models and cancer types, and that JAG2 is a c-MYC-regulated gene, the PDGFRβ-c-MYC-JAG2 pathways would be a logical and expected mechanism of MB carcinogenesis." (PMID 25576913, 2015). "JAG2, a direct target of tRF/miR-1280, plays a role of a Delta-like Notch ligand which combines Notch 1 and Notch 2 receptors and promotes CRC metastasis through the regulation of cancer self-renewal." (PMID 36072340, 2022). "Expression of HPRT1, Jag2, AURKA, and PGK1 were elevated when compared to normal samples, and HPRT1 and PGK1 showed a stepwise elevation in expression that was significantly related to cancer grade." (PMID 30679932, 2019). "Indeed, some tRFs inhibit cell proliferation and metastasis in cancer cells through diverse mechanism such as destabilization of YBP-1, inhibiting Notch signaling by targeting JAG2, or suppressing protein synthesis." (PMID 30596759, 2018). "Furthermore, the networks related to cell cycle, cancer and nervous system development and function showed that several genes such as Nfkb2, NFκBia, BRCA1, Vegf, Jag2, Notch1, EGR1, FoxS1 and collagen type I were regulated by TNF." (PMID 20967264, 2010). "Analysis revealed overexpression of APH1A, CTBP1, HEY1, HEY2, JAG2, NOTCH4 regardless of the cancer subtype." (PMID 41463075, 2025). "Among the ligands, DELTA1 (DLL1) expression was strongly and significantly decreased in cancer tissues, whereas JAGGED1 (JAG1) and JAGGED2 (JAG2) mRNA levels were not significantly changed." (PMID 25167871, 2014). "In addition, JAG2, NOTCH1, and NOTCH3 tend to increase after anti-cancer therapy, although there is no significance." (PMID 39074091, 2024).
infection (8 papers, 2013 to 2025). The state of being infected such as from the introduction of a foreign agent such as serum, vaccine, antigenic substance or organism. "Therefore, JAG-1-shRNA2, JAG-2-shRNA4, and DLL-1-shRNA3 vectors were chosen for subsequent stable infection." (PMID 34940631, 2021). "Upon infection of ST cells and organoids (MOI of 1), the expression of NOTCH1 and JAG2 significantly decreased, in contrast to that of DLL4, whose expression increased." (PMID 41272765, 2025).
adenocarcinoma (3 papers, 2005 to 2022). A common cancer characterized by the presence of malignant glandular cells. "JAG2 mRNA expression was tied to worsening OS in high differentiation adenocarcinoma, HR 3.66 (1.32–10.15), p = 0.008." (PMID 36071128, 2022).
myopathy (2 papers, 2022 to 2024). A disease of the muscle in which the muscle fibers do not function properly. "Thus LGMDR21 shares pathogenic features with EMARDD and JAG2-myopathy, and can be considered a satellite cell-opathy." (PMID 34740639, 2022). "We report clinical features of two additional molecularly confirmed JAG2-related myopathy cases from a consanguineous family, and review the core phenotypic features of our cases and those observed in previously reported cases." (PMID 39649397, 2024). "Notably, patients affected with JAG2-myopathy also display severe reduction of PAX7, concomitant with reduced expression of its target gene MYF5, suggesting a dysfunctional satellite cell niche." (PMID 34740639, 2022).
JAG2 also shares sentences with these, for which no sentence is quoted: multiple myeloma (6 papers); gastric cancer (5); cyst (4); hepatocellular carcinoma (4); breast tumor (3); Alzheimer disease (2); cardiovascular diseases (2); glioblastoma (2); leukemia (2); lung carcinoma (2); ovarian tumors (2); prostate carcinoma (2); serous ovarian cancer (2); acute myeloid leukemia (1); Allergy (1); ataxia-telangiectasia and (1); atherosclerosis (1); B cell lymphoma (1); benign gynecologic tumors (1); cardiomyopathy (1); cervical cancer (1); CNS tumors (1); dementia (1); developmental delay (1); empty follicle syndrome (1); encephalitis (1); head and neck cancer (1); HIV-1 infection (1); Hyperglycemia (1); Hypertension (1).
A further 17 diseases each share a sentence with JAG2 in 1 paper.